EGFR (epidermal growth factor receptor)
Diseases named in the same sentence as EGFR in open-access papers (continued):
Sharing a sentence is not in itself a finding about the gene and the disease.
adenoma (continued). "The staining intensity of EGFR was higher in subgroups of adenomas (grade 2–3: 87.1%) and cancers (grade 2–3: 100%), compared to hyperplastic polyps (max: grade 2) and control group (max: grade 2: 7.5% to 34%) (p < 0.0001)." (PMID 28157706, 2017). "For the first time, we have also demonstrated that there is a gradient of increased EGFR expression during the colorectal carcinogenesis, from adenomas with LGD (overexpression: 10%), and HGD (77.8%), to carcinoma (100%)." (PMID 28157706, 2017). "The primary objective of our study being focused on adenomas, it was necessary to use a primary antibody that was yet validated for EGFR expression in CRC." (PMID 28157706, 2017). "With 77.8% and 100% of overexpression in HGD adenomas and in cancers respectively, the EGFR expression seems higher in our study." (PMID 28157706, 2017). "After completion of endomicroscopy, we euthanized the animals and performed macroscopic imaging of excised colonic mucosa to validate selective uptake of the EGFR peptide in adenomas." (PMID 27874037, 2016). "EGFR (epidermal growth factor receptor), another important molecule that exhibited increased methylation, has been implicated in EMT in adenomas (log2 fold change = 2.9)." (PMID 26101583, 2015). "In conclusion, this study demonstrated a significant correlations between tumor size and the EGFR-positive indices, as well as between EGFR and PR expression in adenocarcinomas and the carcinoma components of carcinomas in adenomas." (PMID 25364399, 2014). "The present study demonstrated significant correlations between tumor size and the EGFR-positive indices, as well as between EGFR and PR expression in adenocarcinomas and the carcinoma components of carcinomas in adenomas." (PMID 25364399, 2014). "Lung tumors, including adenomas, carcinomas in adenomas and adenocarcinomas, were obtained and analyzed by immunohistochemistry for the expression levels of the receptors, ER, PR and EGFR, and PCNA." (PMID 25364399, 2014). "Our observations confirm that the rate of EGFR overexpression increased progressively from normal mucosa, adenoma to tumor tissues." (PMID 23865079, 2013). "High expression of EGFR was found to be 0% (0/20) in the normal mucosa, 5% (1/20) in the adenoma, and 18% (14/76) in the tumor tissues, respectively." (PMID 23865079, 2013). "The expression of EGFR in adrenal tumors indicates a malignant phenotype, which can be used to differentiate carcinomas from adenomas and is a potential target for treatment." (PMID 23198184, 2012). "We show here that acute administration of gefitinib inhibits EGFR signalling while also activating the IGF1R pathway in adenomas developing in the Apcmin/+ mouse, an in vivo physiologically relevant model of intestinal tumourigenesis." (PMID 21811251, 2011). "Disruption of EGFR signaling by either genetic mutation or its kinase inhibition blocks the formation and growth of ACF, microadenomas, and adenomas as well as the growth of established tumors in ApcMin/+ and AOM-treated mice." (PMID 24213116, 2011). "To address this approach, we determined if the acute activity in IGF1R predicted improved outcome (in terms of anti-adenoma effect) when IGF1R inhibition was combined with EGFR blockade." (PMID 21811251, 2011). "Given that K-RAS and B-RAF wild type status is predictive of EGFR-targeted response in patents, we first determined K-ras and B-raf status in adenomas developing in the Apcmin/+ mouse." (PMID 21811251, 2011). "The observation that these adenomas remain wild type for K-ras and B-raf underscores the relevance of this model for studying EGFR blockade." (PMID 21811251, 2011). "In terms of understanding the mechanism of the adenoma suppression with combined EGFR/IGF1R treatment, we undertook protein analysis for 4 h following EGFR and IGF1R blockade alone and in combination." (PMID 21811251, 2011).
adenoma (continued). "This suggests continued EGFR inhibition is required to promote IGF1R adenoma expression and the target of AZ12253801, to elicit an anti-adenoma response." (PMID 21811251, 2011). "The highest incidence of EGFR expression was found in corticotroph adenomas." (PMID 38862897, 2024). "BRAF and EGFR-driven tumors were adenomas and adenocarcinomas." (PMID 37828026, 2023). "Finally, the percentage of adenocarcinomas relative to the adenomas at death was lower in EGFR/MET than EGFR mice, a feature probably related to their shorter survival with less time to allow tumors to become full-blown carcinomas." (PMID 34298655, 2021). "The steadystrengthening of VEGFR and the relative strengthening of EGFR pathwayscompared to the adenoma network are particularly important resultsbecause the relevance of these pathways is clinically proven as thesesignaling pathways are involved in the treatment of advanced coloncancer." (PMID 33562960, 2021). "Whole exome sequencing of corticotroph adenomas enriched with aggressive adenomas identified USP8 mutations in only 5 of 22 adenomas, but another study found EGFR expression in the cytoplasm of 29 of 52 CD adenomas, and protein expression associated with recurrence." (PMID 34867776, 2021). "Her adenoma was positive for EGFR and ErbB2 on immunohistochemistry." (PMID 34867776, 2021). "Therefore, altered expression of multiple EGFR regulators, together with enhanced EGFR expression, coordinately promotes EGFR-ERK signaling in adenoma cells." (PMID 30974867, 2019). "LCRCs more often develop from the classical adenoma-carcinoma sequence of carcinogenesis with aneuploidy and chromosomal instability, leading to amplification of regions hosting receptor tyrosine kinases such as epidermal growth factor receptor (EGFR)." (PMID 31150437, 2019). "However, the clinical significance of EGFR and its relationship to adenoma recurrence in corticotroph adenomas are still obscure." (PMID 31798535, 2019). "In addition to the altered expression of EGFR regulators, expression of EGFR itself is also increased in adenomas compared to the normal epithelium." (PMID 30974867, 2019). "Moreover, EGFR expression was markedly increased in adenomas of ApcΔ716 mice, as well as adenoma-derived organoids and CHIR99021-treated organoids." (PMID 29872037, 2018). "Repression of LGR5 further increases the sensitivity of adenoma cells to EGFR inhibition." (PMID 29149105, 2018). "The specificity of EGFR to adenomas and the gradient of their expression across the grade of dysplasia are two interesting findings for the conception of further fluorescence nanoparticle able to bind EGFR and that would be delivered during colonoscopy." (PMID 28157706, 2017). "Adenomas also expressed more EGFR than their adjacent (p < 0.0001) or distal (p < 0.0001) mucosa." (PMID 28157706, 2017). "Indeed, samples issued from biopsies are known to be exposed to heterogeneous bias, as well as EGFR expression is known to show a heterogeneous staining pattern, also in adenomas." (PMID 28157706, 2017). "To recently, we had the largest series of adenomas on which EGFR expression was measured." (PMID 28157706, 2017). "The level of EGFR expression being significantly higher in adenomas compared to normal colorectal mucosa, this receptor can be validated as a surface biomarker of colorectal adenomas, and should be considered as an interesting target in the development of further nanotechnologies." (PMID 28157706, 2017).
adenoma (continued). "All adenomatous lesions and cancers expressed EGFR with higher proportions of labeled cells per sample (Adenomas: 54.9% grade 2–3; cancers: 100% grade 3), compared to hyperplastic polyps (grade 2–3: 0%) or normal colonic mucosa issued from the control group (grade 2–3: 9.4%–28.3%) (p < 0.01)." (PMID 28157706, 2017). "Furthermore, the role of USP8 and EGFR protein expression was assessed by immunohistochemistry in a subset of 25 adenomas." (PMID 28005997, 2016). "p-EGFR (Y1068) and EGFR levels were higher in 2AD mouse adenomas." (PMID 27683110, 2016). "Furthermore, EGFR expression demonstrated a significant correlation with PR expression, as was also observed in the carcinoma components in carcinomas in adenomas." (PMID 25364399, 2014). "No specific activating mutation in EGFR network is observed in the depressed lesions although these tumors behave more aggressive than protruded adenomas and LSTs." (PMID 25551625, 2014). "We next tested the effects of acute EGFR blockade using gefitinib in adenoma bearing Apcmin/+ mice." (PMID 21811251, 2011). "Therefore in terms of understanding the signalling responsible for combinatorial adenoma suppression we conclude that relative to vehicle, a reduction in EGFR and AKT phosphorylation appears to be important." (PMID 21811251, 2011). "Constitutive KRAS mutations, found in about 50% of all CRCs and in advanced adenomas, drive persistent activation of the RAF/MEK/ERK mitogen-activated protein kinase (MAPK) cascade and the PI3K/AKT pathway independently of upstream signals, including the epidermal growth factor receptor (EGFR)." (PMID 41294868, 2025). "Another immunohistochemical study was performed in 380 adenomas for differences in molecular Ki-67, COX-2, TGFβRI, EGFR, β-catenin, cyclin D1, c-MYC and TUNEL (apoptosis) mutations of proximal and distal adenomas, which may contribute for cancer heterogeneity between the two topographies." (PMID 33759958, 2021). "Importantly, the knockdown of LGR5 increases the sensitivity of adenoma cells to the EGFR inhibitor gefitinib, suggesting low LGR5 expression could be used clinically to predict patients who may benefit from EGFR therapies." (PMID 29149105, 2018). "In demonstrating EGFR blockade enhanced IGF1R activity we have provided support for the in vivo proof of concept that IGF1R-targeted therapy may induce an anti-adenoma effect in adenomas expressing high receptor levels driven by continued EGFR blockade, and is a potential predictive biomarker." (PMID 21811251, 2011). "In research on pituitary samples obtained from patients with growth hormone-producing adenomas, the overexpression of EGFL7 positively correlated with the activation of EGFR (p-EGFR)." (PMID 37446128, 2023). "Overexpression of FZD9, a receptor to Wnt proteins, further links adenomas from female patients with EGF, as the EGFR pathway interacts with Wnt/ßcatenin signalling." (PMID 32183012, 2020). "Upregulating EGFR signaling leads to ACTH overproduction and adenoma growth in corticotroph adenomas." (PMID 31798535, 2019). "Altogether, these results indicate that EGFR signalling is a predominant driver for basal ERK activity and spontaneous ERK activity pulses in adenoma-derived organoids." (PMID 29872037, 2018). "The levels of the EGFR were higher along with β-catenin and pan-RAS, especially in the polyp/adenoma and adenocarcinoma regions of the CRC patient tissues, compare with paired normal tissues." (PMID 30459318, 2018). "A well significant gradient of increased EGFR expression was observed between adjacent mucosa, hyperplastic lesions, low grade dysplasia (LGD) (n = 30), high grade dysplasia (HGD) adenomas (n = 9) and cancers (p < 0.0001)." (PMID 28157706, 2017). "Despite CRC are also lesions with heterogeneity, there is at least adenoma with HGD, which are lesions with EGFR overexpression in 77.8% in our study." (PMID 28157706, 2017).
adenoma (continued). "Analysis of EGFR and USP8 staining intensities and clinical-pathological data of the respective adenomas revealed several correlations." (PMID 28005997, 2016). "Although, the adenomas tended to be larger than the other types of tumors, all of the immunohistochemical labeling indices (PCNA, ER, PR and EGFR) tended to be lower when compared with the carcinomas in the adenomas and adenocarcinoma groups." (PMID 25364399, 2014). "A strong expression of PR, EGFR and PCNA was observed in the carcinoma component of carcinomas in adenomas, in contrast to the peripheral adenoma component." (PMID 25364399, 2014). "This suggests that, in the setting of chronic blockade of EGFR, activation of the IGF1R pathway is mediating adenoma growth through alternative, unidentified mechanisms." (PMID 21811251, 2011). "Chronic monotherapy against either EGFR or IGF1R influences adenoma growth, but combination EGFR/IGF1R blockade produced the most effective adenoma suppression." (PMID 21811251, 2011). "A systematic review published by INCISE identified 49 gene mutations, single nucleotide polymorphisms, or haplotypes in 23 different genes/chromosomal regions (including KRAS, APC, EGFR, and COX1/2) that predicted metachronous adenoma or advanced adenoma development." (PMID 37158435, 2023). "More than 50% of prolactinomas express EGFR and 25% express ErbB2 protein (reviewed in, with 40% of invasive adenomas staining positive for ErbB2, compared to 1.2% of noninvasive adenomas." (PMID 34867776, 2021). "We then sought to determine the influence of Anthos treatment on the Src- and EGFR-related pathways in an ETBF-treated ApcMin/+ mouse model, which have been reported to have increased EGFR activity and c-Src expression in the adenoma and intestinal enterocyte tissue." (PMID 34926717, 2021). "There were 14 EGFR-positive adenomas in 20 (70%) recurrent adenomas and 15 EGFR-positive adenomas in 32 (46.9%) non-recurrent adenomas." (PMID 31798535, 2019). "Densitometric analysis showed significantly greater increases in p-EGFR and p-Erk levels in the recurrent adenomas than in the non-recurrent adenomas (all p < 0.05)." (PMID 31798535, 2019). "p-EGFR and p-Erk were upregulated in recurrent adenomas but were not upregulated in non-recurrent adenomas or in normal pituitary glands, while the total Erk, total Akt, and p-Akt levels were unchanged." (PMID 31798535, 2019). "The expression levels of EGFR, phosphorylated EGFR (p-EGFR) and p-Erk were significantly up-regulated in the recurrent adenoma group compared with those in the non-recurrent adenoma group (all p < 0.05)." (PMID 31798535, 2019). "EGFR, a subtype of the ErbB receptors, which include EGFR (ErbB1, HER1), p185her2/neu (ErbB2, HER2), ErbB3 (HER3), and ErbB4 (HER4), can regulate cell motility and adhesion, adenoma invasion, angiogenesis, and adenoma cell proliferation." (PMID 31798535, 2019). "Stimulation of the epidermal growth factor receptor (EGFR) leads to the activation of KRAS or phosphatidylinositol-3-kinase pathways, which is important in CRC development from early adenoma to intermediate adenoma." (PMID 29568751, 2018). "LGR5 has an important role in the EGF-mediated survival and proliferation of early adenoma cells and could have clinical utility in predicting response of CRC patients to EGFR therapy." (PMID 29149105, 2018). "EGFR and its ligand EGF are highly expressed in corticotroph adenoma cells in up to 75% of corticotroph tumors as well as normal pituitary cells, gonadotroph, somatotroph, and lactotroph adenoma cells." (PMID 28529722, 2017). "EGFR overexpression was reported in 100% of cancers, 77.8% of HGD, and 10% of LGD adenomas." (PMID 28157706, 2017). "Similarly, the carcinoma components of carcinomas in adenomas demonstrated significant correlations between tumor size and PCNA expression, as well as between EGFR and PR expression." (PMID 25364399, 2014).
adenoma (continued). "It appears that adenoma cells in an attempt to overcome EGFR blockade also increase EGFR protein but fail to increase activation of EGFR signalling as shown by an absence of change in EGFR phosphorylation and reduced ERK phosphorylation." (PMID 21811251, 2011). "Moreover, the EGFR signal transducing molecules p-EGFR, p-Akt and p-Erk were upregulated in EGFR-overexpressing adenomas but not in EGFR-negative adenomas." (PMID 38862897, 2024). "In addition, two independent CRC cohorts from the oncomine database indicated that the mRNA level of EGFR in the CRC tissues including adenoma, carcinoma, or adenocarcinoma is higher than that in the normal colon tissues." (PMID 30459318, 2018). "Nor the topography, nor the form of adenomas were related with the level of EGFR expression." (PMID 28157706, 2017). "In this study, the expression levels of epidermal growth factor receptor (EGFR) and cyclin D1 were assessed in 96 tissue samples, including non-tumorous tissue, adenoma, and carcinoma." (PMID 35723316, 2022). "Interestingly, the expression of EGFR was significantly higher in recurrent adenomas than in non-recurrent adenomas, indicating that EGFR may be considered a potential biomarker to determine and predict the recurrence likelihood of pituitary corticotroph adenomas." (PMID 31798535, 2019). "Moreover, the EGFR signal transducing molecules p-EGFR, p-Akt and p-Erk were upregulated in EGFR-overexpressing adenomas but not in EGFR-negative adenomas or normal pituitary glands, indicating that EGFR and its downstream signaling pathway may be involved in adenomaigenesis." (PMID 31798535, 2019). "Moreover, the expression of EGFR was positively correlated with ACTH and cortisol levels but not with age, sex, or adenoma size." (PMID 38862897, 2024). "Moreover, the expression levels of EGFR were positively correlated with ACTH and cortisol levels but not with age, sex, or adenoma size." (PMID 31798535, 2019).